STAT3 (signal transducer and activator of transcription 3)
Diseases named in the same sentence as STAT3 in open-access papers (continued):
Sharing a sentence is not in itself a finding about the gene and the disease.
breast cancer (continued). "Stat3 inhibition in cells grown to high densities was shown to trigger apoptosis in non-neoplastic mouse fibroblasts and epithelial cells as well as breast cancer lines, which is accompanied by a dramatic reduction in Cx43 levels and GJIC." (PMID 30717267, 2019). "A breast cancer cell study demonstrated that Pin1 enhances STAT3 transcriptional activity by interacting with Ser727-phosphorylated STAT3." (PMID 31795496, 2019). "It was shown that the activation of an IL-6/STAT3/PTEN/NF-κB inflammatory feedback loop mediates trastuzumab resistance in HER+ breast cancer cells by expanding the CSC population." (PMID 31557902, 2019). "SHP-1 has been reported to negatively regulate the phosphorylation of STAT3 during tumor development, including in the formation of leukemias, as well as in gastric and breast cancers." (PMID 31117333, 2019). "Nevertheless, STAT3 is over-activated in many breast cancers, while STAT5 promotes both survival and differentiation of mammary epithelium." (PMID 31247937, 2019). "In conclusion, dovitinib induced both apoptosis and autophagy to block the growth of breast cancer cells by regulating the SHP-1-dependent STAT3 inhibition." (PMID 31485222, 2019). "In prostate cancer, metformin represses EMT and metastasis by targeting the COX2/PGE2/STAT3 axis, while in breast cancer the AKT/mTOR/ZEB1 pathway was involved." (PMID 30918838, 2019). "Clearly, this evidence indicates STAT3 is constitutively activated in the mammary tumors and contributes to cell transformation, progression, and survival in human breast cancer." (PMID 31485222, 2019). "In view of the well-documented functions of the IL-6/STAT3 signaling pathway in tumor growth promotion, we examined its role in macrophage-mediated breast cancer cell proliferation." (PMID 30736340, 2019). "In the present study, we indicated that PIM1 was transcriptional activated by IL-6/STAT3 axis and was critical for IL-6 induced breast cancer cell EMT and stemness." (PMID 30989585, 2019). "In breast cancer cells, IL-6 expression activates STAT3 which subsequently upregulate the expression of IL-6 creating an IL-6/STAT3 autocrine loop allowing for continual activation of the axis to drive tumour growth." (PMID 31383893, 2019). "Bioinformatics, small molecule inhibitor, inducible CRISPR/Cas9 KO, and overexpression experiments strongly implicate STAT3 and p300 as mechanotransducers during breast cancer." (PMID 31015465, 2019). "By inhibiting STAT3 activation using AG-490, both osteolysis and tumor growth of breast cancer were strongly alleviated." (PMID 31040267, 2019). "Even though a direct link between PD-L1 and STAT3 has been described in previous reports, in this study it was shown that STAT3 can influence immune response and PD-L1 expression in mouse models as well as in patients with early breast cancer." (PMID 31581535, 2019). "We have reported that pY23-Anxa2 binds to and enhances STAT3 activation and promotes invasion and metastasis of breast cancer cells." (PMID 31113450, 2019). "Adipocytes induce epithelial mesenchymal transition of breast cancer cells through paracrine IL-6/Stat3 signalling." (PMID 31383893, 2019). "In summary, our data strongly suggests that carnosol inhibits STAT3 pathway through a breast cancer-specific mechanism." (PMID 31456939, 2019). "Both the WNT and the STAT3 pathways are often altered in solid tumors including breast cancer, correlating with enhanced tumor cells migration, invasion and metastasis." (PMID 30654518, 2019). "Src is also a well-known upstream kinase of STAT3, and enhanced STAT3 activation confers invasiveness of drug-resistant breast cancer cells." (PMID 31113450, 2019). "We report, in this study, its novel tumor suppressive roles via CSC control on breast cancer cells and the STAT3/IL6 axis and NFkB signaling that drive this functionality." (PMID 31709178, 2019).
breast cancer (continued). "It has been demonstrated that leptin regulates the cell cycle and increases breast cancer cell growth by inducing cyclin D1 expression via STAT3 activation." (PMID 31380268, 2019). "Previous studies have shown that MRE11 overexpression in breast cancer cells leads to cell proliferation by stimulating STAT3 signalling and enhances migration and invasion capabilities through activation of MMP-2 and MMP-9." (PMID 31221177, 2019). "Our studies demonstrate for the first time that the function of MMP2 and MMP9 in breast cancer cell migration, which is mediated by interactions between ERα-36 and STAT3." (PMID 31409371, 2019). "We discussed the correlation of PAK1/IL-6 and Stat3/IL-6 in breast cancer patient from the publicly available dataset such as TCGA (The cancer genome atlas)." (PMID 31658701, 2019). "This then inhibits NF-κB-dependent production of IL-6, STAT3 activation, and IL-6/STAT3-driven cell migration and invasion of breast cancer cells, thereby establishing an IL-6/STAT3/NF-κB/miR-146a negative feedback loop." (PMID 31557902, 2019). "Several reports have described the therapeutic potency of knocking down Notch-1, STAT3, and β-catenin proteins in breast cancer using siRNA." (PMID 31357721, 2019). "In the present study, the role of STAT3 in the regulation of PD-L1 expression and in the potential modifications of the immune microenvironment in breast cancer was investigated." (PMID 31581535, 2019). "The inhibitory effect of ODZ10117 on tyrosine-phosphorylated STAT3 was greater than the known inhibitors in breast cancer cells that are persistently activated or activated by IL-6-stimulation." (PMID 31684051, 2019). "Interleukin 6 (IL6) was discovered to induce the conversion of non-BCSCs into BCSCs by activating OCT4 transcription through STAT3, thereby increasing the self-renewal activity of breast cancer cells." (PMID 31324052, 2019). "Blocking of STAT3 phosphorylation in vivo effectively inhibits osteolysis and tumor growth of metastatic breast cancer." (PMID 31040267, 2019). "Here, it was shown that STAT3 regulated PD-L1 expression in breast cancer cell lines and its silencing led to restriction of tumor growth and altered the immune profile in a murine breast cancer model." (PMID 31581535, 2019). "In the current study, we describe a therapeutic potential of single and combinations of siRNA designed for silencing Notch-1, Wnt/β-catenin, and STAT3 in MCF7_DoxS (wild type) and MCF7_DoxR (doxorubicin resistant) breast cancer cells." (PMID 31357721, 2019). "IL-6 has been found to stimulate STAT3 in breast cancer-derived MDSCs, and the unregulated expression of IDO was through the activation of STAT3 and NF-κB pathway." (PMID 30998767, 2019). "These researches disclosed that Stat3 inhibition provides a rational approach to the treatment of breast cancer." (PMID 31649548, 2019). "It has been shown that leptin promotes the development and progression of breast cancer neoplastic cells by activating the JAK2/STAT3 pathway." (PMID 31380268, 2019). "Consistent with a previous report in colorectal cancer lines, we observed a marked increase in phosphorylated STAT3 after MEK1/2 inhibition in breast cancer lines, suggesting an acute rewiring of compensatory pathway upon MEK1/2 inhibition." (PMID 30777101, 2019). "The role of SHP-1 activity-mediated downregulation of p-STAT3 was also confirmed, thus providing novel mechanistic insight into this molecular target for breast cancer." (PMID 31485222, 2019). "Other studies have found that PL also exerts its anticancer effects via inhibition of the STAT3 and Akt/mTOR signaling pathways in breast cancer cell lines." (PMID 31739520, 2019). "Blocking the Stat3 signaling pathway inhibits the growth of CD44high/CD24low stem cell-like breast cancer cells." (PMID 31019654, 2019).
breast cancer (continued). "In HER2-positive breast cancer, IL-6 can also induce the production and maintenance of breast cancer stem cells (CSCs) through nuclear factor kappa-B (NF-κB) and STAT3 signaling pathways, then promoting tumor progression." (PMID 31500658, 2019). "In this study, we isolated a sesquiterpenoid from Farfarae Flos and examined its inhibitory effect on STAT3 activation inducing apoptosis in MDA-MB-231 human breast cancer cells both in vitro and in vivo." (PMID 31337063, 2019). "In this study, STAT3-mediated regulation of PD-L1 and modulation of immune microenvironment were shown in breast cancer." (PMID 31581535, 2019). "NOTCH activation through NO facilitates constitutive IL-6-dependent STAT3 activation, promoting breast cancer stemness." (PMID 30885232, 2019). "Immunosuppressive activities of TAMs correlate with over-activated STAT3 signaling, whereas disruption of TAMs STAT3 activity can enhance rat immune response to breast cancer." (PMID 31480382, 2019). "Toward understanding the mechanisms of breast cancer progression, we have previously reported that STAT3 promotes breast cancer cell migration by regulating Cyr61 and Myl9 expression." (PMID 31409371, 2019). "Taken together, these results demonstrate that SIRT4 enhances the tamoxifen sensitivity of breast cancer cells by inhibiting the STAT3 signaling pathway." (PMID 31573734, 2019). "The IL-6/JAK1/STAT3 signaling pathway is also important and sufficient in the conversion of non-CSCs into CSCs through regulation of Oct4 expression in human breast cancer lines." (PMID 31557902, 2019). "In fact, it was observed that STAT3-dependent upregulation of Notch-3, Jagged-1, and carbonic anhydrase IX correlates with growth and invasion of breast cancer cells to bone." (PMID 31847214, 2019). "Blocking the expression of STAT3 by shRNA treatment in mouse breast cancer cells was shown to inhibit tumor growth, progression, and metastasis." (PMID 31252615, 2019). "In this study, we developed a doxorubicin resistant MCF7 breast cancer cell line, followed by study of the expression status of important oncogenes including STAT3, β-catenin, and Notch-1." (PMID 31357721, 2019). "In this study, the biologic effects of STAT3 on immune checkpoint expression and anti-tumor responses were investigated in breast cancer (BC)." (PMID 31581535, 2019). "It has been reported that adipocyte-derived IL-6 promoted the up-regulation of PLOD2 in breast cancer cells via activating JAK/STAT3 and PI3K/AKT pathways." (PMID 31170987, 2019). "For example, signal transducer and activator of transcription 3 binds directly to the human Twist1 promoter and activates its transcriptional activity in human breast cancer, hepatocellular carcinoma, and gastric cancer cell lines." (PMID 31383001, 2019). "Later they found that similar cell death was observed in human gastric, primary glioblastoma, and breast cancer cells after transfection with STAT3 siRNA." (PMID 30847297, 2019). "STAT3 targeting through AG-490 is a potential therapeutic strategy for mitigating osteolysis and tumor growth of bone metastatic breast cancer." (PMID 31040267, 2019). "In brief, dovitinib had induced autophagy in breast cancer cells through inhibiting STAT3/Mcl-1 axis and resulted in the formation of autophagy." (PMID 31485222, 2019). "Signaling via JAK2/STAT3 is a critical regulatory component in carcinogenesis in breast cancer related to obesity." (PMID 31380268, 2019). "exerted anti-breast cancer metastasis activities via impairing the Stat3 signaling pathway in part while improved apoptosis in breast cancer cells by mitochondrial-related pathway." (PMID 31649548, 2019). "This analysis revealed that much higher concentrations of each major flavonoid are needed to affect p-STAT3 levels in breast cancer cells when used in pure form in comparison with the whole MH solution." (PMID 31491838, 2019).
breast cancer (continued). "This suggestion is supported by the fact that constitutively activated STAT3 has been documented in several types of tumors, including breast cancer." (PMID 31456939, 2019). "We recently reported that human adipocytes induced EMT occur via the IL-6/STAT3 axis in breast cancer cells." (PMID 31383893, 2019). "A positive association between leptin expression, LEPR, aromatase and MAPK and STAT3 activation has been suggested using tissue samples of patients with estrogen receptor positive breast cancer." (PMID 31380268, 2019). "STAT3 is constitutively activated in all breast cancer subtypes and predominantly in triple-negative cancers." (PMID 31756890, 2019). "In breast cancer, GL extract reduces the number of breast cancer stem cells (BCSCs) by downregulating the STAT3 pathway to inhibit the invasion ability of cancer cells." (PMID 31636686, 2019). "STAT3/p-STAT3 expression level in breast cancer tissues was higher than that in normal ones (OR = 7.48, 95% CI = 5.64–9.94)." (PMID 31375715, 2019). "In conclusion, the occurrence of breast cancer has a close correlation with STAT3/p-STAT3 overexpression and phosphorylation." (PMID 31375715, 2019). "Among other downregulated lncRNAs, WDFY3‐AS2 has recently been reported with TGF‐B‐induced EMT of breast cancer cells through hnRNP‐R modulated positive regulation of STAT3 and WDFY3." (PMID 30959550, 2019). "A hybrid of lipid and polymer vesicles with calcium phosphate as the solid kernel (CaP@HA) was used to introduce STAT3-specific decoy oligonucleotides (STAT3-decoy-ODNs) into TRAZ-resistant HER2-positive breast cancer cells." (PMID 30847297, 2019). "In this study, we showed that dovitinib inactivates STAT3 through SHP-1 to suppress the growth of human breast cancer via induction of both apoptosis and autophagy." (PMID 31485222, 2019). "We found that PAK1 interacts with JAK2 and Stat3, and then activates Stat3 signaling to support mammosphere formation and stemness of breast cancer cells." (PMID 31658701, 2019). "There is abundant evidence to show that elevated levels or abnormal activation of STAT3 contribute to cancer cell proliferation, including breast cancer, prostate cancer, colon cancer, and leukemia." (PMID 31747963, 2019). "STAT3 protein has been shown to be constitutively active in a large number of tumor tissues, including those derived from breast cancer patients." (PMID 31058868, 2019). "This study demonstrates that SIRT4 enhances the sensitivity of breast cancer to tamoxifen via STAT3 pathway inhibition due to decreased STAT3 Y705 phosphorylation." (PMID 31573734, 2019). "Information about STAT3/p-STAT3 expression and clinical data about breast cancer in China in particular were gathered from PubMed, Web of Science, CNKI and WanFang databases." (PMID 31375715, 2019). "Collectively, many studies have reported that honokiol effectively inhibits EMT in breast cancer cells, evidence has been found to support a cross-talk between honokiol and Stat3/Zeb1/E-cadherin axis." (PMID 31877856, 2019). "Ectopic expression of STAT3 rescued the breast cancer cells from cell apoptosis induced by dovitinib." (PMID 31485222, 2019). "ODZ10117 treatment resulted in a dramatic decrease in the level of tyrosine-phosphorylated STAT3 in various breast cancer cells." (PMID 31684051, 2019). "The results demonstrated that the STAT3/p-STAT3 expression level in breast cancer tissue was higher than that in normal ones." (PMID 31375715, 2019). "Specifically, higher level of tyrosine phosphorylated STAT3 was observed in TNBC subtype of breast cancer cells than those of other subtypes." (PMID 31684051, 2019). "A recent study found that the inactivation of STAT3 is able to rescue chemo-resistance in breast cancer." (PMID 32010177, 2019).
breast cancer (continued). "At least in breast cancer, a critical mechanism stimulated by STAT3 to regulate stemness involves genes in fatty acid oxidation and the ability of STAT3 to adjust the levels of reactive oxygen species (ROS) produced in mitochondria." (PMID 31557897, 2019). "The interactions of PD-L1 with STAT3, pro-tumoral macrophages and tumor characteristics have been explored as well in a well-characterized cohort of breast cancer patients." (PMID 31581535, 2019). "More specifically, knocking down Stat3 gene using a specific shRNA plasmid in mouse mammary carcinoma 4T1 cells (shStat3 cells) resulted in decreased levels of pd-l1 compared to cells transduced with corresponding empty vector (shCTR cells)." (PMID 31581535, 2019). "This study reveals that IL-6 receptor gp130 is contained in breast cancer cell-derived exosomes and stimulates STAT3 signaling in bone marrow-derived macrophages (BMDMs)." (PMID 29867925, 2018). "A recent study has revealed that autophagy regulates enrichment of ALDH+ve cancer stem-like cells via EGFR/Stat3 signaling in PyMT murine mammary cancer." (PMID 29455658, 2018). "By the use of in vitro and in vivo approaches, they provide evidence that, under hypoxic conditions in the osteoblast niche, LIF receptor/STAT3 signaling confers a dormancy phenotype to disseminated breast cancer cells." (PMID 30231553, 2018). "By contrast, eriocalyxin B inhibits STAT3 through a covalent binding to Cys712, that is closed to the SH2 domain of STAT3, as evidenced using LC-MS/MS, in order to block STAT3 phosphorylation and cell apoptosis of lung and breast cancer cells." (PMID 29921764, 2018). "STAT3 overexpression indicates poor prognosis in various malignancies, such as hepatic cancer, breast cancer, thyroid cancer, gastric cancer, and melanoma." (PMID 29560131, 2018). "The activation of Janus kinase (JAK)-2/STAT-3 signaling regulates the growth and maintenance of stem-like breast cancer cells (CD44+CD24−)." (PMID 30373171, 2018). "We recently reported that HDACs inhibition leads to STAT3 dephosphorylation via protein tyrosine phosphatase SHP-1 activation in breast cancer cells." (PMID 29545751, 2018). "We did detect multiple associations with miR-20a-5p and miR-20b-5p, which were identified in the literature as a miRNA involved in STAT3 circuits in breast cancer and gliomas respectively." (PMID 30603058, 2018). "We have previously shown that STAT3 was transcriptionally regulating telomerase reverse transcriptase (hTERT) in human breast cancer cells." (PMID 30250641, 2018). "Accordingly, we present an updated meta-analysis of the literature on the expression of STAT3 and p-STAT3 in patients with breast cancer." (PMID 29560131, 2018). "IL-6 mainly promotes the expression of multiple genes through STAT3, thus regulating breast cancer drug resistance." (PMID 30175384, 2018). "Constitutive STAT3 Tyr705 phosphorylation and activation is found in most cancers such as breast cancer and HNSCC." (PMID 29545751, 2018). "For example, STAT3 activation occurs in more than 40% of breast cancers, most often in the triple negative subtype that lack estrogen receptor, progesterone receptor and Human Epidermal Growth Factor 2 (HER2) amplification." (PMID 29588647, 2018). "A recent study has shown that TRIM14 enhanced the STAT3 signaling pathway in breast cancer cells, which plays a critical role in CRC progression." (PMID 30555277, 2018). "In breast cancer, as in physiological contexts, STAT3 can be activated by cytokine receptors, particularly receptors for interleukin-6 (IL-6) family cytokines, including the OSM receptor, as described in the second phase of involution." (PMID 29875329, 2018). "All of these findings suggest that PERK is a key regulator to convey stress signals from the endoplasmic reticulum to the nucleus and illustrate a crucial role for the novel PERK/STAT3/NF-κB/TNFα axis in E2-induced apoptosis in E2-deprived breast cancer cells." (PMID 29531812, 2018).